IL10 (interleukin 10)
Diseases named in the same sentence as IL10 in open-access papers (continued):
Sharing a sentence is not in itself a finding about the gene and the disease.
tumor (continued). "The ability of the MCs to promote tumor growth by upregulating IL-10 expression does not become available until the late stages." (PMID 38602556, 2024). "Subsequently, the ELISA results of the tumor tissue demonstrated that the higher levels of TNF-α and IL-6 in hNVs, hNVs-EGCG and hNVs@Flu-EGCG groups and lower levels of IL-10 in hNVs, hNVs-EGCG and hNVs@Flu-EGCG groups compared to PBS and PLGA-Flu groups, showed the same result as before." (PMID 38637848, 2024). "Depletion of Tregs promotes tumour growth, as demonstrated by Noy and Pollard’s research: CD4+ Tregs are immune-suppressive, directly reducing the ability of CD8+ cytotoxic T cells to fight tumours by secreting IL-10 and transforming growth factor β." (PMID 38339377, 2024). "Selectively inactivating it upregulates MHC-II and decreases IL-10 and arginase, which may become a potential method to regulate the immune response of TME to halt tumor progression." (PMID 38590651, 2024). "Overall, positive associations between IL-6, IL-10, TNF-α, and inflammatory scores with all-cause mortality were evident among cases with non-triple-negative tumours but not among those with triple-negative tumours." (PMID 39342063, 2024). "The present study suggests that aspirin can inhibit specific aspects of T cell function by reducing interleukin-10 and transforming growth factor-β1 secretion via the TIGIT-BCL2-BAX signaling pathway, resulting in improved effector T cell function that inhibits tumor progression." (PMID 39113892, 2024). "However, immunosuppressive factors in the tumor microenvironment, such as TGF-β and IL-10, often impair the anti-tumor function of NK cells, leading to their functional depletion." (PMID 39906665, 2024). "Nevertheless, the association between the upregulation of cytokines TGF-β, IL-4/IL-13, IL-10, IL-6, and IL-2 and the overexpression of FAP across multiple tumor types highlights a crucial link between FAP+ CAFs, tumor progression, and evasion of immune surveillance." (PMID 39035007, 2024). "Quantitative PCR revealed nearly 4.5 fold-decrease of IL-10 and 1.5 fold-increase of IL-12p35 transcripts due to NLGP addition to tumor-conditioned cells, both of which were gradually counterbalanced by Laminarin, Dectin-1 siRNA and their combined inhibitory effects." (PMID 38649988, 2024). "IL‐10 and TGF‐β are known to inhibit the immune response and promote tumor growth." (PMID 39554345, 2024). "Immunosuppressive cytokines in the TME, such as IL-10 and transforming growth factor (TGF)-β, further inhibit DC maturation and promote the differentiation of regulatory T cells (Tregs), which suppress T cell responses and enhance tumor progression." (PMID 39769351, 2024). "In pancreatic cancer, however, B cells support tumor progression through the production of IL-35 rather than IL-10, with immunosuppressive effects confirmed in mouse models." (PMID 39519376, 2024). "Tumor cells often express or secrete soluble mediators such as IL-10, TGF-β, and prostaglandin E2 that dampen the anti-tumor response or polarize immune populations toward anti-inflammatory phenotypes, yielding T regulatory cells, M2 macrophages, and myeloid-derived suppressor cells." (PMID 38550613, 2024). "miR-1246+ exosomes are internalized by adjacent macrophages, inducing the polarization of macrophages from M1 to M2, and secreting pro-tumor factors such as IL-10, TGF-β, and MMP, thus inducing an anti-inflammatory tumor microenvironment and promoting tumor progression." (PMID 39766882, 2024). "On combination treatment with anti-CTLA4 (Ipilimumab), besides depletion of Treg and lowering of IL10 release, the spatial dynamics between CTL and Treg affected the incremental efficacy in tumor killing on combination treatment correlated with significant increase in distance between CTL and Treg." (PMID 38383563, 2024).
tumor (continued). "In the TME, TAMs and tumor cells interact through mediators such as TGF-β, vascular endothelial growth factor (VEGF), platelet-derived growth factor (PDGF), M-CSF, IL-10, chemokine C-X-C motif ligand (CXCL), and extracellular vesicles (EVs) to affect tumor progression." (PMID 39170620, 2024). "The pro-tumor microenvironment of CLL is already sustained by suppressive soluble factors (e.g., IL-10, TGF-β) and inhibitory immune molecules (e.g., PD-L1, LAG3), among which the tolerogenic milieu would only be compounded by therapeutics that induce immunosuppressive DAMP release from CLL cells." (PMID 39767763, 2024). "It is the resident TAMs of the CNS and secretes immunosuppressive factors like interleukin-10 (IL-10) and transforming growth factor-β (TGF-β) or other anti-tumor stimulating factors like IL-12 and tumor necrosis factor-α (TNF-α) based on the “heat” or “cold” status of the TME." (PMID 38720342, 2024). "Results showed that IL4R-Exo(si/mi) successfully decreased the levels of M2 markers and cytokines, including Arg-1, TFG-β, IL-10, and IL-4 and increased the expression of M1 cytokines, including IL-12 and IFN-γ in the lymphomononculear population of tumor tissues." (PMID 39000385, 2024). "M-MDSCs are rapidly recruited to the inflammatory tumor tissues upon exposure to chemokines such as CCL2, CCL5, CXCL8, and CXCL12 and produce multiple immunosuppressive cytokines such as ARG1, nitric oxide (NO), TGF-β, and IL-10." (PMID 38520006, 2024). "In addition, IL-10 induces the overexpression of Foxp3 in CD4+ T cells, increasing the number of Tregs in the tumor." (PMID 39085255, 2024). "However, tumour cells can evade NK cells via a variety of strategies, such as the secretion of cytokines such as TGF-β, IL-10, and prostaglandin E2 (PGE2)." (PMID 38475858, 2024). "Moreover, IL-10 recruited Tregs44,45, and the inhibition of STAT3 and NF-κB reduced the tumor secretion of IL-1044,46." (PMID 39085255, 2024). "MDSCs facilitate tumor invasion and metastasis, predominantly through factors like Indoleamine 2,3-dioxygenase (IDO), Arginase-1 (ARG1), Reactive Oxygen Species (ROS), IL-10, Inducible Nitric Oxide Synthase (iNOS), Cyclooxygenase-2 (COX-2), and Nitric Oxide (NO)." (PMID 38545114, 2024). "MSCs secrete various cytokines and growth factors, such as TGF-β, IL-10, and VEGF, which can modulate the immune response and promote angiogenesis, creating a microenvironment that may favor tumor growth." (PMID 39576660, 2024). "Additionally, because of their plasticity, CD4+ T cells can convert into Treg cells secreting IL-10 and TGF-β, suppressing immune responses and aiding in tumor immune escape." (PMID 38292868, 2024). "Consequently, in anti-tumor immunity, CD3 on HLA-DR+ T cells not only enhances inflammatory responses but also helps maintain immune homeostasis via the IL-10 feed-forward regulatory mechanism." (PMID 39496002, 2024). "In addition, TAMs express immunosuppressive factors, such as IL-10 and transforming growth factor-β (TGF-β), which play a crucial role in suppressing anti-tumor immune responses." (PMID 39403370, 2024). "These neuroendocrine mediators elevate inflammatory cytokines (e.g., IL-6, IL-8) and immunosuppressive cytokines (e.g., IL-4, IL-10, VEGF), suppressing NK cell and Tc cell activity while promoting regulatory T (Treg) cell expansion, ultimately contributing to tumor progression." (PMID 39597826, 2024).
tumor (continued). "M2-like TAMs release anti-inflammatory cytokines such as IL-10, prostaglandin E2, TGF-β, matrix metalloproteinases (MMPs) and VEGF, inhibiting the immune surveillance of tumours, promoting tumour growth and metastasis, and participating in angiogenesis, tissue repair, remodeling and other processes." (PMID 38475858, 2024). "The infiltration of Tregs cells in tumor tissue promotes the progression of HCC, and their secretion of negative immunomodulatory factors (Foxp3, TGF-β, and IL-10) is associated with activation of the Wnt/β-catenin signaling pathway." (PMID 38426090, 2024). "Among cases with non-metastatic tumours (stages I-III), IL-10 showed a positive association with all-cause mortality (HR1-SD 1.32, 95% CI 1.09–1.59)." (PMID 39342063, 2024). "However, once the tumor is established, infected keratinocytes are also reported to release the anti-inflammatory cytokines TGF-β and IL-10, down-modulating the activation of LCs." (PMID 39459945, 2024). "When the JAK-STAT pathway is dysregulated in HCC cells, immunosuppressive cytokines such as IL-10 and TGF-β may be produced to inhibit the function of TILs and impair their ability to infiltrate and attack HCC cells, thereby facilitating tumor immune evasion." (PMID 38426090, 2024). "However, some tumors secrete immunosuppressive cytokines like interleukin-10 (IL-10), which activate STAT3 in immune cells, leading to the suppression of antitumor responses and promoting tumor immune evasion." (PMID 39483536, 2024). "Importantly, Treg cells within the tumor were found to directly suppress the cytotoxic ability and IFN-γ secretion of γδ T cells, with this effect being dependent on TGF-β and IL-10." (PMID 38338658, 2024). "The DMPtNPS@cGAMP + RT group exhibited a significant increase in anti‐tumor cytokines, namely IFN‐γ, IFN‐α, IFN‐β, TNF‐α, and IL‐2, and a more pronounced decrease in pro‐tumor cytokines, including IL‐1β, IL‐10, IL‐4, and TGF‐β, as measured by ELISA kits, in comparison to the other treatment groups." (PMID 38063844, 2024). "In addition the production of immune-suppressive cytokines such as cellular IL-10, viral IL-10 and TGF-beta will favor the appearance of TAMs which will further accelerate the tumor spread." (PMID 38893091, 2024). "These cells secrete cytokines such as IL-10 and TGF-β, which inhibit the activation and proliferation of cytotoxic T cells and natural killer (NK) cells, thereby fostering an environment that protects the tumor from immune attack." (PMID 39712021, 2024). "The consequence of this is a reduction in the secretion of TGF-β and IL-10, an increase in type I interferon levels (which activates NK cells, DCs, CD4+ T cells, and CD8+ T cells), stimulation of NK cells, and augmentation of anti-tumor immunity." (PMID 38426090, 2024). "Taken together, our findings indicate that increased numbers of M2 TAMs in the tumor foci of EC patients increase IL-10 expression, which stimulates IFN-γ release from CD8+ T cells, leading to IDO1 expression by EC cells and the attenuation of tumor-infiltrating CD8+ T cell responses." (PMID 38540186, 2024). "Nevertheless, this cytokine, through the IL-10/STAT3 or TLR4/IL-10 signaling pathways, promotes the formation of M2 macrophages and activates the expression of the genes responsible for anti-apoptotic, pro-tumor and immunosuppressive activity." (PMID 39057050, 2024). "Tumor cells are not passive players in this process; for instance, thymoma and melanoma cells can actively stimulate B cells to produce IL-10, which subsequently suppresses CD8+ T cell or NK cell IFN-γ expression, thereby promoting tumor growth." (PMID 39519376, 2024). "The autophagosome TRAP released by tumor cells induces macrophages to polarize to the M2 phenotype and upregulates PD-L1 and IL-10 expression in TAMs through the TLR4-MyD88-p38-STAT3 signaling pathway, suppressing T cell proliferation and promoting tumor growth." (PMID 38762484, 2024).
tumor (continued). "IL-10 secreted by Bregs suppresses the activity of cytotoxic CD8+ T cells, Th1 and Th17, and induces the conversion of CD4+ T cells to Tregs, thereby promoting tumor immune evasion." (PMID 39085965, 2024). "In tumour microenvironment, CD11b+ dendritic cells with high expression levels of IL23 and TGF‐β could induce IL10+CD4 Tregs and promote tumour progression." (PMID 37748771, 2024). "At this point, macrophages tend to adopt an M2 phenotype characterized by the secretion of immunosuppressive cytokines, such as IL-10, TGF-β, and other cytokines, in order to promote angiogenesis generation, lymphangiogenesis, immunosuppression, and tumor progression." (PMID 39416792, 2024). "Additionally, Tregs inhibit anti-tumor immune response by producing immunosuppressive cytokines, such as TGF-β, IL-10, and IL-35 in the TIME." (PMID 39687617, 2024). "While S100A9, IL-10, and Cxcl2 expression was reduced in a-PD-L1-treated 2F8c tumors compared to tumor controls, no reduction was detected between a-PD-L1-treated and control Egfl6+ tumors." (PMID 39312740, 2024). "M2 macrophages—“bad macrophages,” induced by Th2 cytokines (e.g., IL-4, IL-10, IL-13), produce anti-inflammatory cytokines (e.g., IL-10, IL-13, TGF-β) promoting tumor growth, ECM remodeling to facilitate tumor invasion, metastasis, angiogenesis, and immune suppression." (PMID 39201585, 2024). "Clearly, IL-10 acts as an immunosuppressive factor here, and its reduced levels further confirm that LIPUS may suppress its activity in the tumor microenvironment." (PMID 38349555, 2024). "Conversely, within the TIME, NPC tumor cells hinder the function of DCs by secreting negative regulatory factors, such as IL-10 and vascular endothelial growth factor." (PMID 38755255, 2024). "Notably, M2 macrophages have been shown to promote the growth of malignant cells via the production of IL-10 and VEGF, whereas M1 macrophages inhibit tumor progression by generating ROS." (PMID 39227970, 2024). "IL-10 was initially identified as an immunosuppressive cytokine, but recent researches have also identified the antitumor effect of IL-10 by stimulating CD8 + T cell in tumor models." (PMID 38520006, 2024). "The binding of exogenous adenosine monophosphate (AMP) to the adenosine A2b receptor on TADCs elevates their pro-tumor functions, creating an immunosuppressive environment through the secretion of VEGF, TGF-beta, IL-10, and the expression of cyclooxygenase-2 (COX-2) and IDO." (PMID 39119332, 2024). "The populations of immunosuppressive cells found in immunologically “cold” tumors promote a tolerogenic environment via the release of cytokines and molecules (e.g., IL-10, TGF-β, indoleamine 2,3-dioxygenase (IDO), and CXCL12) inhibiting tumor cell clearance by immune effectors." (PMID 38339258, 2024). "Some cell factors secreted by MON, such as interleukin-6, interleukin-10, and TGF-β, could inhibit lymphocyte activity and promote the growth of tumor cells." (PMID 38540104, 2024). "Tregs are exposed to favorable circumstances inside the tumor microenvironment, which facilitates their growth and survival and aids in the conversion of other T cells into Tregs through cytokines, including TGF-β and tumor-derived IL-10." (PMID 39452154, 2024). "Likewise, the levels of chemokines and cytokines (e.g., IL8; IL10, and TGF‐β) known to favor immune‐suppressive myeloid cells were significantly elevated in AZD4573‐treated tumor homogenates." (PMID 39254172, 2024). "Tregs are a subgroup of inhibitory T cells that play an immunosuppressive role following activation in the body via the secretion of IL-4, IL-10, and TGF-β and participate in the immune escape mechanism of tumours, promoting the occurrence and development of tumours." (PMID 38475858, 2024). "A subset of regulatory B cells, by producing IL-10 and TGF-β, promotes tumor growth and metastasis." (PMID 39519376, 2024).
tumor (continued). "In addition to IL-10 and VEGF in the EOC tumor microenvironment, our results indicate that Lect2 is another novel modulator of PD-L1 expression in MDSC." (PMID 38177412, 2024). "Deviations in IL-10 and IL-12p35 levels in these groups were compared to a control, where mBMDCs were tumor-conditioned and NLGP treated without any receptor neutralization." (PMID 38649988, 2024). "GB cells secrete immunosuppressive factors such as TGFβ2, PGE-2, IL-1, IL-10 (check Section 2.1) and indoleamine 2,3-dioxygenase (IDO), which work cooperatively to suppress the activity of effector cells and to evading the anti-tumor immune response." (PMID 38473776, 2024). "Seemingly, the negative impact of IL10 and ferritin is not due to M2 macrophage–mediated tumour tolerance." (PMID 39259401, 2024). "It is hypothesized that IL-10 could phosphorylate and activate STAT1, STAT3, STAT5, and PI3K pathways, exerting apoptosis regulation and tumor progression functions on immune cells." (PMID 38279997, 2024). "Through different time points analysis, we found that MSA-2 significantly stimulated TNF-α, IL-10, IL-6 and INF-β expression in both plasma and tumor and this expression reached the highest level around 4–6 days after MSA-2 injection and down to normal spectrum after 16 days." (PMID 38592428, 2024). "Scholars have stated that kefir reduces tumor cell viability and growth rates, regulates cytokine expression in tumor tissues (e.g., downregulates IL-6, IL-10 and IL-1β, upregulates TNF-α, IL-10, and IL-4), promotes apoptosis, and exerts immune-enhancing effects." (PMID 39605907, 2024). "While IL-4, IL-6, and IL-10 demonstrated a rise from baseline to tumor response, none of these changes reached statistical significance." (PMID 38022654, 2023). "In addition, it reduced IL-1β, IL-4, IL-6, IL-10, and IL-13 levels, down-regulated PI3K, ERK1/2, and up-regulated EGFR levels, improving the anti-tumor effects of the tumor suppressor microenvironment." (PMID 37397393, 2023). "A498 and 786-O ccRCC tumor cell lines were tested with an extensive set of candidate cytokines, including a combination of IL-10 and IFN-γ; however, none induced HHLA2 expression in these cell lines." (PMID 37891555, 2023). "In addition, YFJP significantly reduced the expression of inflammatory and immunosuppressive cytokines, including IL-1β, IL-6 and IL-10, while increased the expression of cellular effectors TNF-α and IFN-γ in serum and tumor tissues." (PMID 37355637, 2023). "M2-like macrophages suppress immune responses by secreting anti-inflammatory cytokines (e.g., IL-10, TGF-β) and promote angiogenesis by secreting pro-angiogenic factors (e.g., matrix metalloproteinases and VEGF), which accelerate tumor recurrence and metastasis and ultimately promote EC progression." (PMID 37810971, 2023). "Tumor cells secrete TGF-β and prostaglandin E2 (PGE2) to induce DCs to differentiate into regulatory DCs, which inhibit the immune response by secreting cytokines such as IL-10." (PMID 38002256, 2023). "For instance, Treg cells are thought to be suppressors of overactive immunological responses by producing CTLA4, IL-10, and TGF, which may allow tumor cells to evade the immune system." (PMID 37860186, 2023). "Importantly, tumor cells can secret cytokines, including TGF-beta, IL-6, IL10, and VEGF, which commonly lead to the upregulation of PD-1/PD-L1 expression to evade immune detection." (PMID 37880708, 2023). "Additionally, TAMs secrete large amounts of immunosuppressive cytokine IL10, which prevents tumor cell-killing activity of CD8+ T cells, Th1 cells, and NK cells, thereby limiting cytotoxicity of the TME to help in tumor growth." (PMID 38035101, 2023). "RD@MBs significantly reduced the secretion of IL-10 and increased IL-12, indicating that the combined treatment of R837 and DTX effectively induced the polarization of macrophages in the tumor microenvironment and evidently activated the antitumor inflammatory immune response." (PMID 36759928, 2023).